APOE (apolipoprotein E)
Diseases named in the same sentence as APOE in open-access papers (continued):
Sharing a sentence is not in itself a finding about the gene and the disease.
uremia (13 papers, 2009 to 2025). A clinical syndrome associated with the retention of renal waste products or uremic toxins in the blood. "Moderate uremia causes thickening of the aortic valves in apoE-/- mice, which can be attenuated by ACE inhibition." (PMID 19257900, 2009). "In addition, uremia further accelerates both atherosclerotic lesions and arterial calcification in ApoE-deficient mice." (PMID 31440854, 2019). "Uremia and even mild renal dysfunction have been reported to cause a dramatic increase in plaque size and aggressive morphology (foam cell rich soft plaques) in ApoE-/- mice." (PMID 23547749, 2013). "Subtotal nephrectomy and STZ, combined with a diabetic diet, caused uremia in ApoE-KO mice and in double-KO TRIB3 and ApoE mice (ApoE/TRIB3 KO)." (PMID 39932798, 2025). "Carotid wire injury was performed on C57BL/6 wt and apolipoprotein E knockout (Apoe−/−) mice two weeks after induction of uremia by 5/6 nephrectomy." (PMID 28747676, 2017). "Apolipoprotein E-deficient (ApoE) and C57 control female mice underwent an ovariectomy (OVX) or sham surgery and after 2 months, creatinine clearance, uremia and proteinuria were determined." (PMID 25422135, 2014). "The nephrectomized apoE-/- mouse constitutes a new model for investigating the mechanisms of uremia-induced aortic valve disease, and also provides an opportunity to study its pharmacologic prevention." (PMID 19257900, 2009). "The present study demonstrates a novel mouse model of aortic valve thickening, the uremic apoE-/- mouse, and reveals a potential treatment of uremia-induced valvular pathology by an ACE inhibitor." (PMID 19257900, 2009). "Different protocols, diets, strains, techniques, and facilities likely underpin the variable results but taken together, the plurality of evidence suggests that a uremia‐only setting is insufficient to induce both a vulnerable and larger plaque phenotype in ApoE−/− mice." (PMID 38979792, 2024). "This association between lower frequency of ApoE ε4 allele and higher ADMA levels in ESRD may indicate a new way to approach atherogenesis in the inflammatory state of uremia." (PMID 26790728, 2016). "Despite this observation, ApoE mice also have greater levels of uremia and increased renal oxidative stress, indicating that although the glomerular filtration rate was not significantly altered, these animals may already present a reduced renal reserve." (PMID 25422135, 2014). "We chose the nephrectomized apoE-/- mouse, which develops extensive vascular disease and is already an established animal model in the study of uremic atherosclerosis and could thus serve as a suitable model of uremia-induced AS." (PMID 19257900, 2009). "After 36 weeks of uremia, we examined the effect of ACE inhibition on maximal valve thickness in the 5/6 NX apoE-/- mice." (PMID 19257900, 2009). "Our data show an increased uremia in ApoE mice without additive effect of aging, in agreement with others." (PMID 22117541, 2011). "However, ovariectomy did not modify uremia in either C57 OVX (60 ± 4 mg/dL) or ApoE OVX when compared to their respective controls." (PMID 25422135, 2014). "This change could reduce the urea reabsorption, with consequent increased excretion of urea in the urine, which could not be true for the ApoE mouse that already present high uremia at young age." (PMID 22117541, 2011).
Abdominal obesity (12 papers, 2011 to 2025). Excessive fat around the stomach and abdomen. "In a study using an olfactometer, abdominal obesity was negatively correlated to olfactory processing speed in elderly females expressing the apolipoprotein E ε4 allele, a genetic risk factor for Alzheimer’s disease." (PMID 33441955, 2021). "This is the first study to show that the supplementation with LPHs markedly ameliorates the generation of the steatotic liver caused by the intake of a Western diet and reduces abdominal obesity in ApoE−/− mice." (PMID 34439470, 2021). "In presence of abdominal obesity, the lipid-lipoprotein profile is as deteriorated in ApoE2/4 carriers as in carriers of other ApoE genotypes, with the exception of the TG-rich lipoprotein fractions that are higher in ApoE2/2 carriers." (PMID 26605088, 2015). "The minor Arg allele of the Cys112Arg in the APOE gene was associated with an increased prevalence of low HDL-cholesterol levels (PR/allele 1.21, 95% CI 1.07; 1.37) and an increased prevalence of abdominal obesity (PR/allele 1.12, 95% CI 1.03; 1.23)." (PMID 21767357, 2011). "Therefore, the aim of this study was to evaluate the effect of LPHs on abdominal obesity and liver status of ApoE−/− mice fed a WD." (PMID 34439470, 2021). "Two SNPs, CETP Ile405Val and APOE Cys112Arg, were associated with both the prevalence of low HDL-cholesterol level (Ile405Val P = < .0001; Cys112Arg P = 0.001) and with the prevalence of abdominal obesity (Ile405Val P = 0.007; Cys112Arg P = 0.007)." (PMID 21767357, 2011). "Our results suggest that abdominal obesity, defined by an elevated waist circumference (>90 cm in men or 85 cm in women), affects HDL and TG concentrations as well as the cholesterol/HDL-cholesterol ratio in ApoE2/4 carriers similar to what is observed for other ApoE genotypes." (PMID 26605088, 2015).
angina pectoris (12 papers, 2013 to 2024). The symptom of paroxysmal pain consequent to MYOCARDIAL ISCHEMIA usually of distinctive character, location and radiation. "Several case–control studies have shown associations between APOE E4 allele and IHD in populations including participants with MI, angina pectoris, coronary stenosis, coronary angioplasty or coronary artery bypass surgery." (PMID 35332187, 2022).
calcification (12 papers, 2014 to 2025). Process by which organic tissue becomes hardened by the physiologic deposit of calcium salts. "The identification of pleiotropic loci and significant genes, such as those associated with the APOE region and other genes on chromosomes 1, 6, 7, 9, and 19, underscores the shared genetic susceptibility between vascular calcification, AD, and cognitive traits." (PMID 40149595, 2025). "In the present study, bioinformatics analysis of the GSE159832 dataset uncovered that Fth1 is a differentially expressed gene which is significantly upregulated in both ApoE-/- and CKD aortic calcification mice." (PMID 40810067, 2025). "On the contrary, in the TRAIL-/-/ApoE-/- mouse model, TRAIL resulted being protective against vascular calcification, while in dialysis patients circulating TRAIL levels did not associate with vascular calcification." (PMID 30204795, 2018).
colitis (12 papers, 2012 to 2025). Inflammation of the colon. "The anti-inflammatory activity of COG 112 in C. rodentium colitis reduced the inflammatory pattern in ileal samples of APOE −/− and wild-type infected mice." (PMID 41416135, 2025). "In a colitis model, APOE indirectly blocks the production of many inflammatory factors, including gTNF-α, KC, IL-17, and MIP-2, by preventing the nuclear accumulation of NF-kB and the activation of IKK." (PMID 38005265, 2023). "This research was a pioneer in attributing apoE roles in colitis and other intestinal inflammatory conditions and opened new venues to investigate the potential benefits of these compounds against enteropathogens." (PMID 37111572, 2023). "Prior studies have shown that ApoE mimetic peptides inhibited the nitric oxide synthase (iNOS), chemokines, and the NF-KB pathway in a colitis murine model of C. rodentium and reduced LPS-induced vascular adhesion molecule-1 and monocyte adhesion to endothelial cells." (PMID 41416135, 2025). "In addition, ApoE mimetic peptides have been found to inhibit NF-κB signaling in a model of colitis supporting a role of this peptide in the intestinal tract." (PMID 22524518, 2012). "Hence, these findings support the idea that apoE mimetics could be a good target for therapeutic approaches to improve colitis." (PMID 37111572, 2023). "The apoE-mimetic peptide COG112 has been shown to inhibit bacterial-induced expression of iNOS mRNA and protein and NO production, well-known players in colitis pathogenesis." (PMID 37111572, 2023). "The ApoE-mimetic peptide COG112 was shown to block production of many inflammatory factors including TNF-α, KC, IL-17 and MIP-2 potentially by preventing nuclear accumulation of NF-κB and activation of IKK in CECs in a model of colitis." (PMID 27538678, 2016). "Interestingly, the ApoE COG-112 mimetic peptide was found to inhibit NF-κB signaling and downstream pro-inflammatory cytokines in Citrobacter rodentium-induced colitis in mice." (PMID 22524518, 2012).
familial Alzheimer disease (12 papers, 2012 to 2025). A degenerative disease of the brain that causes gradual loss of memory, judgment, and the ability to function socially. "Apolipoprotein E4 (APOE4) is a significant risk for both familial Alzheimer's disease (AD) and sporadic AD with elusive mechanisms." (PMID 40906458, 2025). "Just as APOE Ɛ4 is known to be a genetic predecessor for familial Alzheimer’s disease, Ɛ2 has been reported as being neuroprotective." (PMID 35736443, 2022). "While mutations in APP lead to the development of Familial Alzheimer's Disease (FAD), sporadic AD has only one clear genetic modifier: the ε4 allele of the apolipoprotein E (ApoE) gene." (PMID 22363792, 2012).
Huntington disease (12 papers, 2009 to 2025). Huntington disease (HD) is a rare neurodegenerative disorder of the central nervous system characterized by unwanted choreatic movements, behavioral and psychiatric disturbances and dementia. "In particular, the association of APOE with the AAO for Huntington's disease (HD) was reported in several studies, but the results were inconsistent." (PMID 25369462, 2014).
hypothyroidism (12 papers, 2011 to 2024). Abnormally low levels of thyroid hormone. "The association found between hypothyroidism and cognition remained significant even after adjustment for genetic risk factors like ApoE." (PMID 39659976, 2024). "We observed a positive association between the ages of AD and hypothyroidism onset after accounting for APOE-Ɛ4 (correlation: 0.44, 0.24, 0.60; odds ratio: 1.09, 1.05–1.14)." (PMID 34573243, 2021). "Our findings suggest that APOE Ɛ4 and early age of hypothyroidism may each contribute independently to the risk for early AD onset in the DS population." (PMID 34573243, 2021). "However, an early age of hypothyroidism onset and the presence of the APOE-Ɛ4 allele were independently associated with the early age of AD onset." (PMID 34573243, 2021). "Alternatively, as the APOE ε4 allele has been reported to be positively associated with hypothyroidism, this mechanism might also be related to compensation." (PMID 32671080, 2020). "As expected, the presence of an APOE Ɛ4 allele was associated with an earlier onset of AD in DS, as has been reported by others; however, we did not detect an interaction between the presence of the APOE Ɛ4 allele and the relationship between the age of onset of AD and age of hypothyroidism onset." (PMID 34573243, 2021). "Among patients with available data, differences in the distributions of demographics, hypothyroidism variables (presence, age of onset), thyroid function tests, thyroid autoantibodies, and APOE genotypes were assessed (e.g., chi-squared, Mann–Whitney tests)." (PMID 34573243, 2021). "In conclusion, our study suggests that the early onset of hypothyroidism in DS is significantly associated with an early onset age of AD, and that it is independent of APOE Ɛ4 allele status, BMI, vitamin B12 status, or presence of OSA." (PMID 34573243, 2021).
Intellectual disability (12 papers, 2012 to 2026). "Models controlled for chronological age, sex, study site, premorbid intellectual disability level, APOE e4 allele carrier status, psychiatric diagnoses, and psychiatric medication use." (PMID 40217501, 2025). "Our haplotype analysis using rs676387-rs605059-rs598126 revealed that the carriers of haplotype TCC had earlier onset of AD, after adjusting for the presence of an APOE ε4, allele level of intellectual disability, ethnicity, and BMI (hazard ratio = 1.8, 95% CI, 1.1–3.1)." (PMID 22474448, 2012). "We suggest that the presence of an APOE-ε4 allele in the genotype will accelerate the development of AD and result in an earlier onset, regardless of other factors (sex, ethnicity, and the level of intellectual disability), as it does in the general population." (PMID 34279450, 2021). "Age, gender, apolipoprotein E status and level of intellectual disability were included as covariates." (PMID 37920115, 2023). "After adjusting for the covariates of APOE-ε4 status, ethnicity, and level of intellectual disability, men with DS had 1.53 times the hazard of AD (95% CI: 1.03–2.29) compared with women with DS." (PMID 34279450, 2021). "Competing risk survival analyses were used to determine the effect of sex alone and after adjustment for APOE-ε4 status, ethnicity, and level of intellectual disability (ID)." (PMID 34279450, 2021). "A model that included level of intellectual disability explained more of the variance in adult attentional abilities but did not alter the pattern of effects of age and its interaction with APOE group (eResults in the Supplement)." (PMID 32986108, 2020). "The influence of APOE genotype on cognitive outcomes is moderated by ethnicity and premorbid IQ, positioning low pIQ, a proxy for intellectual disability (ID), as a population more vulnerable to the negative effects of APOE ε4 in older adulthood." (PMID 40697576, 2025).
malnutrition (12 papers, 2012 to 2025). Inadequate nutrition resulting from poor diet, malabsorption, or abnormal nutrient distribution. "This review summarizes the potential role of promising apoE mimetic peptides to improve the function of the gut-brain axis, including targeting the blood-brain barrier in children afflicted with malnutrition and enteric infections." (PMID 37111572, 2023). "In summary, our overall findings suggest that ApoE is one of the key players modulating the intestinal architecture and immune and inflammatory responses following malnutrition and C. parvum infection." (PMID 24586873, 2014). "Altogether our findings suggest that apoE plays a key role in the intestinal restitution and immunoinflammatory responses with Cryptosporidium infection and malnutrition." (PMID 24586873, 2014). "Apolipoliprotein E (apoE), a critical targeting protein in lipid homeostasis, has been found to have immunoinflammatory effects on murine models of infection and malnutrition." (PMID 24586873, 2014). "APOE effects on neurodevelopmental outcomes have been found in children with other stresses, including lead exposure, oxygen deprivation, malnutrition, and cerebral palsy." (PMID 23049896, 2012). "Although the orchestrated epithelial restitution and immune-inflammatory responses against malnutrition and enteric infections constitute a multi-factorial gene-to-gene interplay, the APOE gene appears to enable better intestinal adaptation against Cryptosporidium parvum." (PMID 24586873, 2014). "Malnutrition indicators and FT3 status associated with age but not ApoE genotypes." (PMID 35265656, 2022). "Collectively, these results suggest that TDP related malnutrition and abnormal FT3 level were dependent on age but not ApoE genotypes." (PMID 35265656, 2022). "Malnutrition and FT3 levels depend on age but not apolipoprotein E (ApoE) genotype." (PMID 35265656, 2022).
migraine (12 papers, 2015 to 2025). "The resulting subnetwork included 9 genes: migraine-associated genes APOE, LRP1, CARF, CTIF, RNF213, and ECM1; LAMA2, which is associated with vestibular anomalies in mice; and the neurodevelopment-associated genes MYO5A and KLC2." (PMID 37107589, 2023). "(ApoE) ApoE is implicated in lipid transport and metabolism, and it is involved in different neurological and vascular disorders, including migraine." (PMID 36982428, 2023). "In relation to headache conditions, APOE-2 allele has been identified as a risk factor for migraine, whereas APOE ε4 allele is positively related to headache, including migraine and tension-type headache." (PMID 31623575, 2019). "Several studies have shown a relationship between APOE polymorphism and the expression of the cytokines involved in migraine and TTH." (PMID 26264634, 2015). "The other two reports investigated a possible association of APOE polymorphism with migraine and TTH." (PMID 26264634, 2015). "Apolipoprotein E (ApoE) gene has been reported to be associated with migraine and tension-type headache (TTH), but the results are conflicting." (PMID 26264634, 2015). "Accordingly, ApoE polymorphisms were associated with an increased risk of headaches and migraine." (PMID 36982428, 2023). "ApoE might play an important role in the pathophysiology of migraine, and may act as a diagnostic biomarker of migraine." (PMID 29357368, 2018). "This study aimed to evaluate the association of ApoE with migraine by a meta-analysis." (PMID 26264634, 2015). "Therefore, to define further the disease risk associated with APOE polymorphism, in this study we performed a meta-analysis of all related studies that evaluated allelic and genotypic frequencies of ApoE polymorphism in migraine." (PMID 26264634, 2015). "Moreover, several studies investigated the association between APOE single nucleotide polymorphism (SNP) and migraine, but the results are conflicting." (PMID 26264634, 2015). "Furthermore, APOE polymorphism influences the expression of the cytokines involved in migraine and TTH." (PMID 26264634, 2015). "The majority of the identified variants were found in genes previously associated with migraine (LRP1, ECM1, CARF, CTIF, RNF213, APOE, SLC35D2), with two different rare LRP1 variants each identified in two unrelated children with vertigo." (PMID 37107589, 2023). "Although there have only been a few studies reporting changes in circulating levels, ApoE appears to be a potential biomarker for migraine diagnosis and is worth further investigating." (PMID 36982428, 2023). "In conclusion, the relationship between the pathophysiology of migraine and ApoE has been unclear to date." (PMID 29357368, 2018). "Our analysis revealed that serum ApoE protein can serve as a novel biomarker that reflects the pathogenesis of migraine." (PMID 29357368, 2018). "As a result of our literature search, a total of four published articles reported on the relationship between APOE SNP and migraine and met the inclusion criteria." (PMID 26264634, 2015). "Indeed, serum ApoE protein levels were higher in EM patients than in HC, particularly during migraine attacks." (PMID 36982428, 2023). "Moreover, ApoE might be a useful biomarker of migraine, especially in patients with MA based on our results." (PMID 29357368, 2018). "ApoE might indirectly play an important role in the pathophysiology of migraine." (PMID 29357368, 2018).